TRIB3 (tribbles pseudokinase 3)
Description:
Inactive protein kinase which acts as a regulator of the integrated stress response (ISR), a process for adaptation to various stress. Inhibits the transcriptional activity of DDIT3/CHOP and is involved in DDIT3/CHOP-dependent cell death during ER stress. May play a role in programmed neuronal cell death but does not appear to affect non-neuronal cells. Acts as a negative feedback regulator of the ATF4-dependent transcription during the ISR: while TRIB3 expression is promoted by ATF4, TRIB3 protein interacts with ATF4 and inhibits ATF4 transcription activity (By similarity). Disrupts insulin signaling by binding directly to Akt kinases and blocking their activation (By similarity). May bind directly to and mask the 'Thr-308' phosphorylation site in AKT1 (By similarity). Interacts with the NF-kappa-B transactivator p65 RELA and inhibits its phosphorylation and thus its transcriptional activation activity. Interacts with MAPK kinases and regulates activation of MAP kinases. Can inhibit APOBEC3A editing of nuclear DNA.
Synonyms: C20orf97; NIPK; SKIP3; TRB3; dJ1103G7.3; SINK
Tractability: Small molecule: it belongs to a druggable protein family. Antibody: its Gene Ontology location is reachable by antibodies, with high confidence. PROTAC: it is named in the literature on targeted protein degradation; ubiquitination databases record sites on it.
Gene: Protein-coding gene on chromosome 20 (362,835 to 397,564, forward strand). Ensembl gene ENSG00000101255.
Subcellular location: Nucleus
Subcellular location (Human Protein Atlas): Nucleoplasm
Pathways (Reactome):
Signal Transduction: Activation of AKT2; Negative regulation of the PI3K/AKT network; PIP3 activates AKT signaling; VEGFR2 mediated vascular permeability
Cellular responses to stimuli: Response of EIF2AK1 (HRI) to heme deficiency; Response of EIF2AK4 (GCN2) to amino acid deficiency
Immune System: CD28 dependent PI3K/Akt signaling
Metabolism: PPARA activates gene expression
Gene Ontology:
Molecular function: kinase activity; protein binding; protein kinase binding; protein kinase inhibitor activity; protein serine/threonine kinase inhibitor activity; mitogen-activated protein kinase kinase binding; transcription corepressor activity; ubiquitin ligase activator activity; ubiquitin protein ligase binding; ubiquitin-protein transferase regulator activity; ATP binding; enzyme binding
Biological process: intrinsic apoptotic signaling pathway in response to endoplasmic reticulum stress; negative regulation of DNA-templated transcription; negative regulation of insulin receptor signaling pathway; negative regulation of MAPK cascade; negative regulation of transcription by RNA polymerase II; regulation of MAP kinase activity; response to endoplasmic reticulum stress; cellular response to insulin stimulus; negative regulation of fat cell differentiation; negative regulation of fatty acid biosynthetic process; positive regulation of proteasomal ubiquitin-dependent protein catabolic process; positive regulation of protein ubiquitination; regulation of autophagy; regulation of D-glucose transmembrane transport
Cellular component: nucleoplasm; nucleus; cytosol; plasma membrane
Genetic constraint (gnomAD): Loss-of-function variants: 21 observed, 18.02 expected, observed/expected ratio (o/e) 1.17, 90% interval 0.82 to 1.66. The upper end of that interval is the gene's LOEUF score, 1.66, which puts it in group 6 of 6, group 1 being the genes least tolerant of losing a copy. Missense variants: 484 observed, 506.71 expected, observed/expected ratio (o/e) 0.96, 90% interval 0.89 to 1.03. Synonymous variants: 208 observed, 225.93 expected, observed/expected ratio (o/e) 0.92, 90% interval 0.82 to 1.03.
Homologues: Orthologues: chimpanzee TRIB3 (97% identical), macaque TRIB3 (93% identical), dog TRIB3 (82% identical), pig TRIB3 (80% identical), mouse Trib3 (73% identical), rat Trib3 (73% identical), guinea pig TRIB3 (68% identical), zebrafish trib3 (49% identical), Drosophila melanogaster trbl (33% identical). Paralogues in human: TRIB1 (44% identical), TRIB2 (42% identical), STK40 (29% identical).
Diseases named in the same sentence as TRIB3 in open-access papers:
TRIB3 is named in the same sentence as 136 diseases in open-access papers, as found by Europe PMC text mining. Sharing a sentence is not in itself a finding about the gene and the disease. The quoted sentences say what the papers report.
breast carcinoma (49 papers, 2009 to 2025). "TRIB3 is overexpressed in various cancer tissues and is closely associated with poor prognosis in patients, including breast cancer, and colorectal cancer, lung cancer." (PMID 39118481, 2024). "Stress-induced TRIB3 expression enhances the resistance of cancer cells to hypoxia and is associated with poor prognosis in breast cancer." (PMID 38235126, 2023). "TRIB3, a member of the Tribbles family of pseudokinases, is often dysregulated in cancer and has been associated with breast cancer initiation and metastasis formation." (PMID 36142452, 2022). "Findings presented in this work support the idea that TRIB3 enhanced expression is associated with good prognosis and a better response to therapy in luminal breast cancer patients." (PMID 34771470, 2021). "TRIB3 expression was associated with increased disease-free survival and a better response to therapy in luminal breast cancer patients." (PMID 34771470, 2021). "For example, high mRNA levels of TRIB3 were associated with a poor outcome while increased protein levels of TRIB3 correlated with good prognosis in the same cohort of breast cancer patients." (PMID 34771470, 2021). "Here we report that expression of the pseudokinase Tribble 3 (TRIB3) positively associates with breast cancer stemness and progression." (PMID 31844113, 2019). "It is found that high TRIB3 mRNA expression is associated with a poor prognosis in both breast cancer and colon cancer." (PMID 23185332, 2012). "TRIB3 is independently associated with poor prognosis of breast cancer patients, possibly through its association with tumor cell hypoxia." (PMID 21864376, 2011). "Examining TRIB3 expression in human breast tumor material revealed that there was an independent association with poor prognosis of breast cancer patients." (PMID 21864376, 2011). "For instance, Tribbles homolog 3 (TRIB3)—a cytokine induced by hypoxia and involved in various cell survival pathways—shows elevated mRNA levels associated with poor prognosis in breast cancer patients, yet paradoxically, high protein expression of TRIB3 is linked to better prognosis." (PMID 40322886, 2025). "For instance, elevated TRIB3 links stress signals to induce breast cancer initiation and progression by supporting breast cancer stemness, and elevated TRIB3 is positively associated with epidermal growth factor receptor (EGFR) stability and non-small cell lung cancer (NSCLC) progression." (PMID 36555349, 2022). "TRIB3 has been reported to be implicated in the breast cancer, lung cancer." (PMID 35499169, 2022). "Interestingly in our study we found that TRIB3 expression is associated with a better response to endocrine therapies in both luminal A and luminal B breast cancer patients." (PMID 34771470, 2021). "Nutrient deprivation or the induction of endoplasmic reticulum stress could upregulate TRIB3 expression in basal-like breast cancer through ubiquitin specific peptidase 9 X-linked (USP9x)-mediated deubiquitination and stabilization of TRIB3." (PMID 30678233, 2019). "In this study, we demonstrated that elevated expression of TRIB3 is positively associated with the initiation and progression of breast cancer as well as with the poor prognosis of breast cancer patients by enhancing breast cancer stemness." (PMID 31844113, 2019). "Recently, we reported opposite associations of TRIB3 mRNA and protein with breast cancer prognosis." (PMID 23185332, 2012). "Thus, miRNA-24 is a potential candidate marker that could explain the opposite association of TRIB3 mRNA and protein with breast cancer prognosis." (PMID 23185332, 2012). "Interleukin (IL-6) can promote transcription of the novel lncRNA AU021063, which stabilizes Trib3 (tribbles homolog 3) to activate Mek/Erk signaling and promote breast cancer metastasis." (PMID 39272915, 2024). "To explore the key pathway by which PB targets TRIB3 in breast cancer, we assessed the phosphorylation levels of PI3K and AKT in MDA-MB-231 cells after PB treatment." (PMID 39881875, 2024).
breast carcinoma (continued). "Tribbles homolog 3 (TRIB3) is a member of the pseudokinase family, many studies have shown that TRIB3 is highly expressed in breast cancer, which is closely related to tumor progression and poor prognosis." (PMID 39881875, 2024). "TRIB3 has been reported to be overexpressed in many different malignant tumors, such as clear cell renal cell carcinoma, lung cancer, breast cancer, and gastric cancer." (PMID 38235126, 2023). "Mechanistically, TRIB3 can facilitate breast cancer stem cells through regulating AKT to interfere with the FOXO1-AKT interaction and inhibit FOXO1 phosphorylation, ubiquitination, and degradation by E3 ligases SKP2 and NEDD4L." (PMID 37732314, 2023). "Previously, TRIB3 was shown to be induced by hypoxia (0.1–0.5% O2) in breast cancer cells and in rat pulmonary artery smooth muscle cells (5% O2), Expression of Ddit4 and Gadd45a were previously shown to be increased under hypoxia and oxidative stress." (PMID 37656229, 2023). "Taken together, our data suggest that TRIB3 modulates PPARγ-mediated growth inhibition by interfering with the MLL complex in MCF7 breast cancer cells." (PMID 36142452, 2022). "TRIB3 levels have been shown to influence breast cancer tumorigenesis and metastasis formation, but little is known about the mechanisms behind such associations." (PMID 36142452, 2022). "In this study, we demonstrate that TRIB3 regulates the expression of PPARγ, a transcription factor that has gained attention as a potential drug target in breast cancer for its antiproliferative actions." (PMID 36142452, 2022). "In fact, we and others have recently shown that TRIB3 localizes in the nucleus in breast cancer cells and that the N-terminal domain of TRIB3 interacts with a number of transcription complexes, including the WRAD complex." (PMID 36142452, 2022). "Our study situates TRIB3 as an epigenetic regulator that controls the expression of PPARG in breast cancer cells." (PMID 36142452, 2022). "In order to better understand the role of TRIB3 in breast cancer cells, we performed the RNA sequencing of TRIB3 knock-down compared to scramble control in the MCF7 cells." (PMID 36142452, 2022). "In this study, we showed that TRIB3 plays a dual role in the regulation of luminal breast cancer cell lines." (PMID 34771470, 2021). "Several studies have shown that TRIB3 is elevated in multiple cancer cell lines and primary tumors including colorectal cancer, breast cancer, and lung cancer." (PMID 34580365, 2021). "In this study we aimed to investigate the role of TRIB3 in luminal breast cancer, the most frequent subtype of this malignancy." (PMID 34771470, 2021). "The existing literature on the role of TRIB3 in breast cancer is limited and relatively contradictory." (PMID 34771470, 2021). "Specifically, our findings point to the existence of a crossed regulation between HER2 and TRIB3 in luminal B breast cancer cells." (PMID 34771470, 2021). "TRIB3 has been shown to be induced by both thapsigargin and hypoxia (0.1–0.5% O2) in breast cancer cells and was found to co-localise with Pimonidazole (a marker of hypoxia) in breast cancer tissue." (PMID 34003246, 2021). "Overexpression of lncRNA-AU021063 in breast cancer cells prolonged the activation of the Mek1/2 and Erk1/2 kinases and increased the production of Trib3 protein under IL6 signaling." (PMID 35126382, 2021). "The expression of TRIB3 is higher in breast cancer, ovarian cancer, lung cancer, and colorectal cancer, and outcomes are poor." (PMID 33841505, 2021). "In this work we found that the increased expression of the protein tribbles pseudokinase 3 (TRIB3) is associated with a good prognosis and a better response to therapy in luminal breast cancer patients." (PMID 34771470, 2021). "As a first approach to investigate the role of TRIB3 in breast cancer, we analyzed the expression of this pseudokinase in public databases." (PMID 34771470, 2021).
breast carcinoma (continued). "We also analyzed TRIB3 protein expression in samples from luminal breast cancer patients and performed bioinformatic analyses in public datasets." (PMID 34771470, 2021). "Mechanistically, Notch has been found to mediate triple negative/basal-like breast cancer radioresistance through BCSC enrichment downstream of tribbles homolog 3 (TRIB3), and in parallel with STAT1." (PMID 34295896, 2021). "Trib3 is induced by IL6 in breast cancer cells, promotes the malignant behavior of ovarian cancer cells through Mek-Erk signaling, and induce cell migration, invasion, and metastasis of liver cancer cells." (PMID 35126382, 2021). "Our data also indicate that TRIB3 inhibits the HER2 pathway in Luminal B (HER2+) breast cancer cells." (PMID 34771470, 2021). "Recent studies have shown that the expression of TRIB3 was found to be elevated in colorectal cancer, breast cancer and lung cancer, and was related to the poor prognosis." (PMID 32874132, 2020). "In breast cancer, TRIB3 expression positively correlates with the spheroid formation in vitro and tumor engraftment efficiency in vivo." (PMID 32874132, 2020). "Existing studies have confirmed that the expression of TRIB3 is increased in solid tumors such as colorectal cancer, melanoma, breast cancer, liver cancer, lung cancer, and leukemia, thereby making it a marker of cancer." (PMID 32874132, 2020). "Given that TRIB3 senses a variety of stress signals, and that enhanced TRIB3 expression leads to poor prognosis for breast cancer patients, we postulated that TRIB3 contributes to the pathogenesis of breast cancer via its tumor initiation capacity." (PMID 31844113, 2019). "We ranked 20,530 genes from breast cancer samples in the TCGA dataset by their relative TRIB3 expression in the top 10th percentile (TRIB3Hi) vs. the bottom 10th percentile (TRIB3Low) for gene-set enrichment analyses." (PMID 31844113, 2019). "Altered expression of HMGA2, POLE2 and TRIB3 was predictive of survival among members of the Metabric breast cancer cohort." (PMID 30763339, 2019). "Our study provides insights into breast cancer development and confers a potential therapeutic strategy against TRIB3-overexpressed breast cancer." (PMID 31844113, 2019). "We proposed that SOX2 rather than other pluripotency factors plays a vital role in supporting the breast cancer stemness in breast cancer with high TRIB3 expression." (PMID 31844113, 2019). "It has been reported that higher TRIB3 expression is a poor prognostic factor in breast cancer patients with radiotherapy." (PMID 30678233, 2019). "Of the 23 co-expressed mRNAs identified through RNA-seq, we demonstrated that overexpression of HMGA2, POLE2 and TRIB3 reduced metastasis-free survival in Metabric Breast Cancer cohort from TCGA, as observed by Kaplan Meier analysis." (PMID 30763339, 2019). "The expression of jagged 1 (JAG1), one of the Notch ligands, was inhibited with knockdown of TRIB3 in breast cancer cells." (PMID 30678233, 2019). "Our work indicates that TRIB3 links stress signals to breast cancer stemness through the coordination of FOXO1 and SOX2 in breast cancer with high TRIB3 expression." (PMID 31844113, 2019). "Here the authors show that TRIB3 enhances breast cancer stemness through interaction with AKT to promote FOXO1 stability, which then increases SOX2 activity." (PMID 31844113, 2019). "Collectively, these data strongly suggest that SOX7 activates SPRY1 and SLIT2, but inhibits MTHFD2 and TRIB3 in breast cancer." (PMID 29757932, 2018). "Downstream of PERK, ATF4 mediates hypoxia-induced breast cancer progression via regulation of tribbles homolog 3 (TRIB3), unc-51-like autophagy activating kinase 1 (ULK1), and lysosomal-associated membrane protein 3 (LAMP3)." (PMID 30248920, 2018). "TRIB3 gene expression, in contrast to TRIB3 protein expression, has been shown to correlate with poor prognosis in patients with breast cancer and a poor prognosis in patients with non-small cell lung cancer (NSCLC)." (PMID 27908682, 2017).